CRP (C-reactive protein)
Diseases named in the same sentence as CRP in open-access papers (continued):
Sharing a sentence is not in itself a finding about the gene and the disease.
diabetes (continued). "The following possible confounders were separately entered as independent variables into model 1 (model 2): plasma fasting glucose, plasma fasting insulin, time since diagnosis of diabetes, heart rate, SBP, DBP, myocardial steatosis, us-CRP and NT pro-BNP." (PMID 27874027, 2016). "Moreover, insulin resistance is associated with an increase in C-reactive protein (CRP), a marker of inflammation which has been shown to increase linearly with the number of metabolic syndrome components present, associated with a higher risk of developing diabetes and CAD." (PMID 27468314, 2016). "The increased risk associated with low lung function remained even after adjustment for age, smoking, physical activity, social class, alcohol intake, BMI, antihypertensive treatment, systolic blood pressure, prevalent diabetes, stroke, AF, LVH and CRP." (PMID 26811343, 2016). "Despite good agreement in the matching criteria, there were significant differences between cases and controls in CRP and ESR, obesity (body mass index (BMI) ≥30 kg/m2), diabetes and use of glucocorticoids." (PMID 27495156, 2016). "Chronic inflammation occurred in the diabetic pancreas accompanied by up-regulation of CCAAT/enhancer-binding protein beta (C/EBPβ) and its targets (TNFα, Il6, CRP, and Fn1) as well as myeloperoxidase (Mpo) and C-X-C chemokine receptor type 2 (Cxcr2)." (PMID 26110898, 2015). "Study participants in the highest baPWV quartiles were more likely to be older, male, or heavy drinkers and have diabetes or hypertension; higher blood pressure, glucose, total cholesterol, triglyceride, ALT, GTP, and CRP; and lower HDL." (PMID 26538347, 2015). "Patients with diabetes and periodontal disease had significantly higher mean levels of serum TNF-α, IL-6 and CRP than healthy subjects (P < 0.001)." (PMID 26644840, 2015). "Examined parameters included BMI, incidence of diabetes, plasma fasting glucose, AGEs, soluble receptor for AGEs and 2,2-diphenyl-1-picrylhydrazyl (DPPH) scavenging, serum C-reactive protein (hsCRP), plasminogen activator inhibitor-1 (PAI-1), and fetuin-A." (PMID 25852219, 2015). "ApN and inflammatory factors are inversely correlated, which was confirmed by the observed significant differences in ApN, CRP, FIB, and HCY according to the type of diabetes." (PMID 26089882, 2015). "We found that plasma OPG levels were positively correlated with age, duration of diabetes, SBP, CRP." (PMID 26260869, 2015). "Both models were adjusted for the following parameters: age ≥60 years, gender, dialysis vintage ≥5 years, diabetes, pre existing CVD, CRP >5 mg/L." (PMID 26322258, 2015). "The prevalence of diabetes, white blood cell count (WBC), ln hs-CRP, ln UPCR levels were higher in patients with BW gain >3.0%." (PMID 26406589, 2015). "There is a significant elevation in the interleukin-6 (IL-6), C-reactive protein (CRP), tumour necrosis factor-alpha (TNF-α) and IL-1β levels in preclinical diabetes samples." (PMID 26596471, 2015). "A recent study of 69 newly diagnosed diabetes subjects demonstrated a positive correlation between serum FGF21 levels and CRP." (PMID 25850006, 2015). "Another finding of this investigation was that vitamin E not only attenuates diabetes-induced Ox-LDL and CRP elevation but also alleviates aorta VSMC proliferation." (PMID 25864817, 2015). "Levels of ApN and HDL were significantly increased in type 1 diabetes in comparison with type 2 diabetes, whereas CRP, FIB, HCY, and GGT were significantly increased in type 2 diabetes, indicating that this type of diabetes is an inflammatory state." (PMID 26089882, 2015). "Plasma OPG levels correlated positively with age(r = 0.410, p < 0.001), duration of diabetes(r = 0.307, p < 0.001), SBP(r = 0.207, p < 0.001) and CRP(r = 0.247, p < 0.001)." (PMID 26260869, 2015).
diabetes (continued). "Compared with those with a lower BMI, female patients with a higher BMI were tend to have an older age, a higher prevalence of diabetes, hypertension and CVD, higher levels of MAP, eGFR, hemoglobin, CRP, and HbA1C." (PMID 25942584, 2015). "Higher systemic levels of C-reactive protein (CRP), and soluble receptors of tumor necrosis factor-alpha (TNF-α), sTNF1 and sTNF2, accompany incident diabetes after initiation of HIV antiretroviral therapy." (PMID 24587328, 2014). "At baseline, body mass index (BMI), smoking, diabetic mellitus, usage of statins, Hs-CRP and APN independently correlated with Hs-CRP/APN ratio as analyzed by spearman rank correlation." (PMID 25070472, 2014). "Diabetes, CAD and age (per 10 years increase) showed an approximately 2-fold increase; hypertension, CRP and male sex showed an approximately 1.3-fold increase while female sex showed a roughly 1.3-fold decrease of risk." (PMID 24465667, 2014). "PEDF was marginally associated with microalbuminuria/albuminuria progression (adjusted HR = 2.63; 95% CI = 0.98–7.08; P = .055), adjusted for sex, age, WC, diabetes duration, HbA1c, SBP, antihypertensive treatment, CRP, and eGFR-EPI." (PMID 25166721, 2014). "Fasting plasma glucose (FPG), HbA1c, and C-reactive protein (CRP) were measured and incident diabetes was identified by the recently updated criteria." (PMID 24819157, 2014). "The mechanisms underlying WML are not fully understood, but the observation that CRP, as a marker of inflammation, may be involved in the pathophysiology of cerebral small vessel disease is in accord with studies that link hypertension and diabetes to vascular dementia and small vessel subtypes." (PMID 24587705, 2014). "COPD patients exhibit elevated levels of inflammatory biomarkers including CRP, TNF-α, fibrinogen, leukocytes, IL-6, and IL-8 suggesting that COPD may be similar to other diseases associated with systemic inflammation including CAD, peripheral arterial disease, osteoporosis and diabetes." (PMID 25480156, 2014). "Hs-CRP levels were significantly augmented in smokers (median mg/L [IQR]: 1.1 [0.6;2.4] vs. 0.7 [0.4;1.5], p = 0.001) and a trend was seen in patients with diabetes (1.1 [0.4;2.3] vs. 0.8 [0.4;1.4], p = 0.06)." (PMID 24465602, 2014). "In multivariable models, VAT was the strongest independent correlate of diabetes, HbA1c, clinical and subclinical CHD and CRP, more so in South Asians than Europeans for HbA1c (P = 0.01 for interaction)." (PMID 24862429, 2014). "As the concentration of cystatin C rose, the levels of age, diabetes duration, carotid and femoral IMT, systolic blood pressure, neutrophils, BUN, Cr, UA and CRP increased, but RBC, Hb, PLT, albumin, FPG, PPG and GFR decreased." (PMID 23843968, 2013). "The prevalence of diabetes, age, both CIMT and CRP were significantly higher in patients with medial artery calcification of the feet than patients without medial artery calcification of the feet." (PMID 23360132, 2013). "The correlation between the CP levels and the extent of heart failure was independent of gender, smoking, alcohol taking, hypertension, diabetes mellitus, AST, uric acid, CKMB, CRP, LVEF, and other parameters." (PMID 23781119, 2013). "There were significant correlations between IMT and; apoB, CRP and systolic blood pressure (SBP) and there were significant correlations between PWV and; diabetes duration, SBP, BMI, WC and SAD." (PMID 23536999, 2013). "BMI, SBP, cholesterol, triglycerides, CRP, cystatin c, serum GGT and diabetes prevalence increased with the age while HDL and serum albumin were opposite." (PMID 23947772, 2013). "The aim of this study was to determine the correlation between pneumonia and the levels of C-reactive protein (CRP) and interleukin-6 (IL-6), as well as to identify early predictors of pneumonia in acute ischemic stroke patients with diabetes mellitus." (PMID 23935729, 2013).
diabetes (continued). "Hypertension, diabetes, recent social pressure, tea drinking, HDL, TC, hs-CRP, SBP and DBP were significant different in these two groups." (PMID 23861874, 2013). "The monocyte count was positively correlated with duration of diabetes, SBP, TC, TG, LDL cholesterol, hs-CRP, mean-CCA-IMT, max-CCA-IMT and UAE, and negatively correlated with HDL cholesterol." (PMID 24373412, 2013). "The individuals with IGR, compared to healthy controls, had higher body mass index (BMI), higher prevalence of hypertension and family history of diabetes, higher levels of FPG, OGTT2h, HOMA-IR, TG and CRP, and lower levels of HOMA-beta and HDL-C." (PMID 22427825, 2012). "C-reactive protein (CRP) is produced in the liver and increased levels of the protein are seen in a variety of disorders including cardiovascular disease, diabetes and various inflammatory conditions." (PMID 22989709, 2012). "Several studies have reported an association between single-nucleotide polymorphisms (SNPs) in the CRP gene with variation in blood levels of CRP, or with CHD, diabetes, microangiopathic stroke, insulin resistance, metabolic syndrome, or hypertension." (PMID 23049543, 2012). "CRP and CVD were the most important predictors of impaired HRQoL, followed by reduced GFR and diabetes." (PMID 22710013, 2012). "In both genders, those with diabetes, hypercholesterolemia, hypertriglyceridemia, low HDL-C, and metabolic syndrome all had significantly higher CRP levels." (PMID 22533665, 2012). "Consistent with this, elevated levels of the proinflammatory cytokines TNF-α, IL-6, and C-reactive protein (CRP) have been shown in individuals with insulin resistance and diabetes." (PMID 22804097, 2012). "In summary, the results of the multiple regression analyses showed that CRP and CVD in the individual were the most prominent predictors for impaired PCS among adults with CKD 2–5, followed by GFR, diabetes and age." (PMID 22710013, 2012). "Individuals reclassified to higher eGFRCKD-EPI categories were more likely to be younger, female, had lower prevalence of diabetes and CVD, and had lower BP, cholesterol, CRP and less albuminuria." (PMID 22702805, 2012). "CRP and CVD emerged as the most important predictors of impaired HRQoL, followed by reduced GFR and diabetes." (PMID 22710013, 2012). "Global markers of inflammation, CRP and MPO levels in plasma, were significantly higher in obese participants with diabetes before treatment compared to controls, supporting the pro-inflammatory state expected in this population." (PMID 23025537, 2012). "Patients with diabetes and the higher hs-PRC at baseline were selected from groups 1 and 2, and hs-CRP oscillations were analyzed." (PMID 22322513, 2012). "Surprisingly, the one-year follow-up mortality rate was influenced by other variables, such as age, history of type 2 diabetes mellitus, HDL-cholesterol levels, C-reactive protein levels, and myoglobin levels." (PMID 22536511, 2012). "We constructed 3 models and used the multiple logistic regression to explore the association of serum total testosterone with NAFLD, after adjusting for variables such as age, diabetes, smoking, exercise, BMI, VAT, HOMA-IR, and hs-CRP." (PMID 22691278, 2012). "In turn, the independent covariables of Tie-2 were diabetes, HDL-C, CRP and triglycerides, and these variables accounted for 12 percent of the variation in Tie-2 levels." (PMID 21672190, 2011). "Circulating levels of FGF21 were found to strongly correlate with serum phosphate, creatine and CRP levels in CKD subjects after adjustment for BMI, gender, age and diabetes mellitus." (PMID 21525989, 2011). "In the Sandy Lake Health and Diabetes Project, leptin, CRP, IL-6 and serum amyloid A were included in a risk model based on cardiometabolic risk factors, adiponectin and impaired glucose tolerance, but could not improve diabetes prediction." (PMID 21674000, 2011).
diabetes (continued). "To distinguish between the acute phase response and the iron metabolism, we further adjusted for CRP, which did not reduce the HR of ferritin substantially, supporting the concept that the ferritin-diabetes association may not reflect the acute phase response but mainly the iron metabolism." (PMID 20396381, 2010). "Several well-known markers of inflammation secreted by the adipose tissue, including IL-6 (which stimulated the hepatic synthesis of CRP), IL-1β and TNF-α, have been referred as independent predictors of diabetes." (PMID 20652060, 2010). "In elderly subjects with diabetes or obesity, longer cumulative averages also resulted in the greatest effects on inflammation in a study of PM2.5 effects on CRP, IL-6, and white blood cells." (PMID 20056584, 2010). "In the Insulin Resistance Atherosclerosis Study, plasma C-reactive protein and PAI-1 levels were enhanced in insulin-resistant subjects who later developed diabetes, and PAI-1 levels predicted diabetes independently of other known risk factors." (PMID 20158910, 2010). "Their high rates of CRP and CVD are likely due to the high prevalence of diabetes, renal disease and obesity; hyperglycemia impedes endothelial function and produces glycation end products that support myocardial dysfunction." (PMID 19668697, 2009). "In the RIO-Lipids study, there was a 29% reduction in the C reactive protein (CRP), and in the RIO-Diabetes study, the CRP reduction was 26%." (PMID 19835615, 2009). "Systemic serum analysis of patients undergoing CABG determined raised resistin and CRP levels, whereas adiponectin levels were decreased, this reduction being exacerbated in CAD patients with diabetes." (PMID 16412224, 2006). "This approach was selected because preliminary descriptive analyses suggested a non-monotonic relationship between diabetes duration and CRP levels." (PMID 41893351, 2026). "Prior to diabetes onset, UCD‐T2DM rats had significantly higher circulating levels of IL‐6 and IL‐1β, and these elevations persisted throughout disease progression, with only CRP showing a significant increase at 8 weeks post‐onset." (PMID 42086336, 2026). "Univariate analysis identified significant associations of age, marital status, family income, physical activity level, education level, total cholesterol, CRP levels, lymphocyte count, WBC count, neutrophil count, HbA1c, prevalent CVD, hypertension, and diabetes." (PMID 41496140, 2026). "Multivariate adjustment for confounders (e.g., age, diabetes, baseline CRP, and renal function) was not performed due to the small number of infection cases, limiting model stability." (PMID 41008500, 2025). "Ultimately, nine variables were included as independent variables: age, primary disease (diabetic nephropathy or not), comorbid diabetes, Hs-CRP, serum phosphorus, iPTH, HDL-C, and VFA levels." (PMID 40276255, 2025). "Gender, race, BMI, education level, PIR, smoking status, diabetes, stroke, lung disease, CHF, CVD, cancer or malignancy, opioids use, NSAIDs use, statins use, WBC, RBC, PLT, BNP and CRP were significantly different in the chronic pain group compared with the non-chronic pain group (P < 0.05)." (PMID 39919114, 2025). "In contrast, patients in the T3 group were more often older and had higher heart rate and hs-CRP levels, STEMI, diabetes, prior HF, previous MI, history of stroke, elevated NT-proBNP, IABP, multivessel or triple-vessel disease, primary PCI, and β-blocker treatment." (PMID 41315962, 2025). "Diabetes status, glucose, CRP, WBC, sex, and mechanical ventilation were not independently associated with mortality in this model." (PMID 41598192, 2025). "The 30-day MACE was significantly predicted by CRP (p < 0.001), age (p = 0.01), troponin (p = 0.001), and time to hospital admission (p = 0.02), but not by sex, diabetes, hypertension, smoking, or reperfusion strategy (all p > 0.05)." (PMID 41200636, 2025).
diabetes (continued). "Physical health outcomes were measured across four studies and covered cancer, high cholesterol, hypertension, diabetes, asthma; migraine, epilepsy, hepatitis, and human immunodeficiency and acquired immunodeficiency syndrome (HIV/AIDS), weight, C-Reactive Protein (CRP) levels and finally death." (PMID 40729394, 2025). "Similar to our findings, a study on LLD in patients with diabetes found elevated markers like CRP and IL-6 but no prediction of dementia over a 10.6-year follow-up." (PMID 39922907, 2025). "Higher HS during pregnancy was associated with lower CRP, HOMA-IR, higher MATSUDA index, and reduced MetS (BMI-based) at one-year postpartum, independent of classical diabetes risk factors (all p ≤ 0.035)." (PMID 41276872, 2025). "Fourth, inflammatory biomarkers (e.g., CRP, salivary cytokines) were not consistently available for all participants, limiting the exploration of biological mechanisms linking diabetes and periodontal inflammation." (PMID 41303234, 2025). "Other covariates (CRP, albumin, diabetes, hypertension, CKD, ischemic heart disease): not statistically significant after adjustment." (PMID 41195122, 2025). "These anti-inflammatory and antioxidant effects have been similarly reported in various pathological models, including colitis, ischemia–reperfusion injury, and diabetes, where MB administration reduced TNF-α, IL-1β, IL-6, and CRP levels, suppressed MPO and MDA, and enhanced SOD activity." (PMID 40870501, 2025). "The presence of prediabetes, diabetes, hypertension, or atherogenic dyslipidemia in obese individuals was not shown to significantly affect inflammatory parameters (CRP, IL-6)." (PMID 40005412, 2025). "Elevated IL-6, CRP, and TNF-α levels have been reported in AD patients with diabetes mellitus." (PMID 41294487, 2025). "Initial univariate analysis of the training cohort (n = 195) identified multiple significant predictors of AF recurrence (all p < 0.05), including AF type (non‐paroxysmal vs paroxysmal), diabetes mellitus, advanced age, LVZ extent, RDW, hs‐CRP, and increased LAD." (PMID 41223074, 2025). "Of the total group, in multivariate linear regression, hs-CRP remained significantly statistically correlated with WBC total (p = 0.034) and with the composite variable from BMI and ATM (p = 0.006) after adjusting with age and diabetes duration." (PMID 40004669, 2025). "However, no significant intergroup differences can be observed regarding WBC, CRP, LDL-C, and history of hypertension, dyslipidemia, and diabetes mellitus between survival and death group." (PMID 40589451, 2025). "The type 2 diabetes mellitus patients withhypertension who had increased hs-CRP levels had a greater incidence of myocardial infraction results death and morbidity when comparedto type 2 diabetes mellitus patients without hypertension." (PMID 40978613, 2025). "We show that CRP is a strong predictor of hospital morbidity and mortality inpatients with acute myocardial infarction who have diabetes with hypertension as well as those who do not have hypertension." (PMID 40978613, 2025). "Additionally, we observed significant correlations between AF recurrence and clinical factors including advanced age, diabetes mellitus, larger LAD, higher serum ST2 and hs-CRP levels, and increased CHA2DS2-VASc scores." (PMID 40842477, 2025). "Studies have documented increased CRP concentrations in individuals with diabetes compared to those without." (PMID 40698663, 2025). "Notably, a high risk of fibrosis was the most significant predictor for patients with MASLD, whereas this was a high CRP concentration for those with NAFLD, followed by diabetes." (PMID 41171731, 2025). "Participants diagnosed with T2DM demonstrated a mean hs-CRP/HDL ratio that was 1.2 times higher than that of individuals without diabetes." (PMID 40123888, 2025).